PSMC3 (proteasome 26S subunit, ATPase 3)
Description:
Component of the 26S proteasome, a multiprotein complex involved in the ATP-dependent degradation of ubiquitinated proteins. This complex plays a key role in the maintenance of protein homeostasis by removing misfolded or damaged proteins, which could impair cellular functions, and by removing proteins whose functions are no longer required. Therefore, the proteasome participates in numerous cellular processes, including cell cycle progression, apoptosis, or DNA damage repair. PSMC3 belongs to the heterohexameric ring of AAA (ATPases associated with diverse cellular activities) proteins that unfolds ubiquitinated target proteins that are concurrently translocated into a proteolytic chamber and degraded into peptides.
Synonyms: TBP-1; TBP1; RPT5; DCIDP; EBNDS
Tractability: Small molecule: an approved drug acts on it; a structure with a bound ligand is known; a high-quality ligand is known. Antibody: its Gene Ontology location is reachable by antibodies, with high confidence. PROTAC: UniProt records ubiquitination sites on it; ubiquitination databases record sites on it; its protein half-life has been measured.
Target class: Enzyme
Gene: Protein-coding gene on chromosome 11 (47,418,765 to 47,426,488, reverse strand). Ensembl gene ENSG00000165916.
Subcellular location: Cytoplasm; Nucleus
Subcellular location (Human Protein Atlas): Cytosol; Nucleoplasm; Nuclear bodies
Pathways (Reactome):
Immune System: AMPK-induced ERAD and lysosome mediated degradation of PD-L1(CD274); Activation of NF-kappaB in B cells; Antigen processing: Ubiquitination & Proteasome degradation; CLEC7A (Dectin-1) signaling; Cross-presentation of soluble exogenous antigens (endosomes); Dectin-1 mediated noncanonical NF-kB signaling; Downstream TCR signaling; ER-Phagosome pathway; FCERI mediated NF-kB activation; GSK3B-mediated proteasomal degradation of PD-L1(CD274); Interleukin-1 signaling; NIK-->noncanonical NF-kB signaling; Neutrophil degranulation; SPOP-mediated proteasomal degradation of PD-L1(CD274); TNFR2 non-canonical NF-kB pathway
Cell Cycle: APC/C:Cdc20 mediated degradation of Securin; APC/C:Cdh1 mediated degradation of Cdc20 and other APC/C:Cdh1 targeted proteins in late mitosis/early G1; Autodegradation of Cdh1 by Cdh1:APC/C; Autodegradation of the E3 ubiquitin ligase COP1; Cdc20:Phospho-APC/C mediated degradation of Cyclin A; FBXL7 down-regulates AURKA during mitotic entry and in early mitosis; G2/M Checkpoints; SCF(Skp2)-mediated degradation of p27/p21; SCF-beta-TrCP mediated degradation of Emi1; Separation of Sister Chromatids; The role of GTSE1 in G2/M progression after G2 checkpoint; Ubiquitin-Mediated Degradation of Phosphorylated Cdc25A; Ubiquitin-dependent degradation of Cyclin D
Signal Transduction: Asymmetric localization of PCP proteins; Degradation of AXIN; Degradation of DVL; Degradation of GLI1 by the proteasome; Degradation of GLI2 by the proteasome; Degradation of beta-catenin by the destruction complex; GLI3 is processed to GLI3R by the proteasome; Hedgehog 'on' state; Hedgehog ligand biogenesis; MAPK6/MAPK4 signaling; Negative regulation of NOTCH4 signaling; Regulation of PTEN stability and activity
and 28 more pathways
Gene Ontology:
Molecular function: identical protein binding; protein binding; proteasome-activating activity; ATP binding; ATP hydrolysis activity
Biological process: host-mediated perturbation of viral transcription; positive regulation of transcription by RNA polymerase II; cellular response to type I interferon; positive regulation of proteasomal protein catabolic process; proteasomal protein catabolic process; proteasome-mediated ubiquitin-dependent protein catabolic process; regulation of proteasomal protein catabolic process; response to oxidative stress
Cellular component: membrane; nucleus; proteasome complex; cytosol; extracellular region; ficolin-1-rich granule lumen; nucleoplasm; P-body; proteasome accessory complex; secretory granule lumen; synaptic vesicle; cytoplasm
Genetic constraint (gnomAD): Loss-of-function variants: 11 observed, 51.72 expected, observed/expected ratio (o/e) 0.21, 90% interval 0.13 to 0.35. The upper end of that interval is the gene's LOEUF score, 0.35, which puts it in group 1 of 6, group 1 being the genes least tolerant of losing a copy. Missense variants: 238 observed, 564.86 expected, observed/expected ratio (o/e) 0.42, 90% interval 0.38 to 0.47. Synonymous variants: 201 observed, 219.85 expected, observed/expected ratio (o/e) 0.91, 90% interval 0.81 to 1.03.
Homologues: Orthologues: chimpanzee PSMC3 (99% identical), macaque PSMC3 (99% identical), mouse Psmc3 (99% identical), pig PSMC3 (99% identical), rabbit PSMC3 (99% identical), dog PSMC3 (99% identical), tropical clawed frog psmc3 (94% identical), rat Psmc3 (92% identical), guinea pig PSMC3 (91% identical), zebrafish psmc3 (91% identical), Drosophila melanogaster Rpt5 (82% identical), Caenorhabditis elegans rpt-5 (78% identical). Paralogues in human: PSMC1 (41% identical), PSMC5 (40% identical), PSMC4 (38% identical), PSMC2 (36% identical), PSMC6 (35% identical).
Diseases named in the same sentence as PSMC3 in open-access papers:
PSMC3 is named in the same sentence as 31 diseases in open-access papers, as found by Europe PMC text mining. Sharing a sentence is not in itself a finding about the gene and the disease. The quoted sentences say what the papers report.
breast carcinoma (4 papers, 2020 to 2024). "The results of high-throughput transcriptomic analysis showed that the expression profile of PSMC3 in breast cancer was significantly higher than that in normal breast tissue, being positively associated with low survival." (PMID 38398629, 2024). "Both mRNA and protein levels of PSMC2, PSMC3, PSMC4, PSMC5, and PSMC6 were significant in cancer tissues, and PSMC1, PSMC3, PSMC4, PSMC5, and PSMC6 overexpression was associated with poor prognoses of breast cancer patients." (PMID 34329194, 2021). "According to our results from an Oncomine analysis of mRNA expressions of PSMC2, PSMC3, PSMC4, PSMC5, and PSMC6, these members are highly upregulated in breast cancer tissues; therefore, we chose breast cancer to perform further bioinformatics analyses." (PMID 34329194, 2021). "Meanwhile, we discovered that high levels of PSMC1, PSMC3, PSMC4, PSMC5, and PSMC6 transcripts were positively correlated with poor survival, which likely shows their importance in breast cancer development." (PMID 34329194, 2021). "The data demonstrated that PSMC1-6 presented moderate protein expressions, and PSMC2, PSMC3, and PSMC5 were highly expressed in certain clinical tissues from breast cancer specimens." (PMID 34329194, 2021). "The present findings showed significantly higher expression profiles of PSMC2, PSMC3, PSMC4, PSMC5, and PSMC6 in breast cancer compared to normal breast tissues." (PMID 34329194, 2021). "Indeed, PSMC2, PSMC3, PSMC4, PSMC5, and PSMC6 were recently reported as highly expressed in breast cancer, which correlated with worse outcomes." (PMID 36498916, 2022). "The Kaplan–Meier plotter database also showed that PSMC1, PSMC3, PSMC4, PSMC5, and PSMC6 had high expression levels in breast cancer tissues may have oncogenic roles in breast cancer progression." (PMID 34329194, 2021).
deafness (3 papers, 2020 to 2022). An inherited or acquired condition characterized by the complete loss of the ability to hear from one or both ears. "A study based on whole-genome sequencing and a Psmc3 knockout zebrafish model shows that mutations in the proteasome subunit Psmc3 can lead to neurosensory syndrome, resulting in proteotoxic stress development, deafness, and cataracts." (PMID 35237384, 2022). "We suggest that biallelic loss of PSMC3 causes a novel autosomal recessive syndrome with varying degrees of neurosensorial dysfunctions including the combination of cataract and deafness." (PMID 32500975, 2020). "Herein, using whole‐genome sequencing, we describe a novel homozygous non‐coding pathogenic variant in PSMC3 associated with severe congenital deafness and early‐onset cataracts and various neurological features in three patients from a very large consanguineous family." (PMID 32500975, 2020). "In this study, we describe a novel homozygous deep intronic splice variant, identified in three patients with an unusual neurosensorial disease combining early‐onset deafness, cataracts and subcutaneous deposits, in PSMC3 encoding one of the proteasome subunit." (PMID 32500975, 2020). "Interestingly, among others PSMC3 was shown to interact with CHMP4B (MIM 610897), ACTG1 (MIM 102560) and GJB6 (MIM 604418) involved in cataract and deafness." (PMID 32500975, 2020).
autism (2 papers, 2020 to 2025). Persistent deficits in social interaction and communication and interaction as well as a markedly restricted repertoire of activity and interest as well as repetitive patterns of behavior. "While PSMG1 has not been directly linked to common NDDs, dysfunction of proteasome-associated genes such as PSMB1 and PSMC3 has been associated with autism, developmental delays, and microcephaly." (PMID 40869915, 2025).
cataract (2 papers, 2020 to 2022). Partial or complete opacity of the crystalline lens of one or both eyes that decreases visual acuity and eventually results in blindness. "Zebrafish modelling for knockout in PSMC3 remarkably reproduced the human phenotype with inner ear development anomalies as well as cataracts, suggesting that Rpt5 plays a major role in inner ear, lens and central nervous system development." (PMID 32500975, 2020).
gastric cancer (2 papers, 2020 to 2021). A primary or metastatic malignant neoplasm involving the stomach. "CircPSMC3, a circular RNA derived from the PSMC3 gene, was originally discovered as a tumour‐suppressor factor for gastric cancer." (PMID 32808450, 2020).
glioma (2 papers, 2021 to 2024). A benign or malignant brain and spinal cord tumor that arises from glial cells (astrocytes, oligodendrocytes, ependymal cells). "PSMC3 was identified as a crucial node in a PPI network in glioma cells." (PMID 34329194, 2021).
kidney renal cancer (2 papers, 2020 to 2023). "Lastly, PSMC3 was found to be an unfavorable prognostic marker in human renal cancer, further supporting its possible involvement in cancer development and immune escape." (PMID 36718025, 2023).
melanoma (2 papers, 2020 to 2023). A malignant, usually aggressive tumor composed of atypical, neoplastic melanocytes. "In summary, these results provide evidence supporting a role of Psmc3 and Ndufa1 in the susceptibility of melanoma cells to CTL‐mediated killing." (PMID 36718025, 2023).
microcephaly (2 papers, 2024 to 2025). A congenital or acquired developmental disorder in which the circumference of the head is smaller than normal for the person's age and sex. "Proteasome subunit mutations in PSMB1, PSMC3, and PSMD12 are associated with craniofacial dysmorphisms in humans, including microcephaly, semicircular canal malformations, and retrognathia and microretrognathia, respectively." (PMID 39171526, 2024).
atherosclerosis (1 paper, 2021). A disease characterized by the build-up of fatty material and calcium deposition in the arterial wall resulting in partial or complete occlusion of the arterial lumen. "Another proteasomal subunit, PSMC3 mutation is associated with subcutaneous calcifications, indicating that this lincRNA RP11-245 J9.5 might be involved in atherosclerosis by regulating several proteasome subunits." (PMID 33568140, 2021).
autism spectrum disorder (1 paper, 2023). A spectrum of developmental disorders that includes autism, and Asperger syndrome. "Of the unique genes, 18 genes were found to be in smaller (<1 MB) focal CNVs in our NDD cohort and we identified PSMC3 gene as a strong candidate gene for Autism Spectrum Disorder (ASD)." (PMID 36959829, 2023).
hepatocellular carcinoma (1 paper, 2022). A malignant tumor that arises from hepatocytes. "However, the protein level of PSMD2 and PSMC3 didn’t change in other NEDD4L-KD turmor cells such as hepatocellular carcinoma (HCC) cells." (PMID 35236820, 2022).
cancer (6 papers, 2021 to 2024). A tumor composed of atypical neoplastic, often pleomorphic cells that invade other tissues. "Interestingly, we discovered that PSMC genes were overexpressed in a subtype-specific manner: specifically, PSMC1, PSMC2, PSMC3, PSMC4 were highly expressed in the triple-negative subtype, PSMC5 in HER-2, and PSMC6 in luminal cancer." (PMID 34329194, 2021).
tumor (3 papers, 2019 to 2021). "TBP-1 (PSMC3) depletion stabilizes FRα (FOSL1) and further increases its levels in tumor cells expressing RAS–ERK pathway oncogenes." (PMID 34503105, 2021). "Depletion of several ubiquitinases and proteasome components (DTX3L, UBE2E1, RNF31, RNF115, USP2, USP42, PSMC3, and PSMD10) were also found to inhibit tumor cell migration." (PMID 31278301, 2019).
neurodevelopmental disorder (2 papers, 2023 to 2024). A behavioral and cognitive disorder with onset during the developmental period that involves impaired or aberrant development of intellectual, motor, or social functions. "More recently, mutations in the subunits of the 19S (the major 20S regulator) RPN5 (PSMD12) or RPT5 (PSMC3) have been linked to neurodevelopmental disorders." (PMID 36980185, 2023). "Previous published work has shown that nonsense or missense variants of proteasome subunits PSMB1, PSMC3, and PSMD12 are associated with neurodevelopmental disorders." (PMID 38776958, 2024). "Furthermore, mutations in genes encoding proteasome subunits result in neurodevelopmental disorders, as exemplified by variants of genes encoding the 20S CP subunit PSMB1 (β1) and the 19S RP subunits PSMC3 and PSMD12." (PMID 38776958, 2024).
bacterial infections (1 paper, 2025). "PSMC3 proteasome subunit variants are linked to the production of type I interferon, which can worsen bacterial infections." (PMID 40867920, 2025).
PSMC3 also shares sentences with these, for which no sentence is quoted: glaucoma (2 papers); Alzheimer disease (1); bladder cancer (1); cervical cancer (1); developmental delays (1); head and neck cancer (1); liver cancer (1); lung adenocarcinoma (1); lung carcinoma (1); Neurodevelopmental delay (1); Obesity (1); ovarian carcinoma (1); pancreatic cancer (1); papillary thyroid carcinoma (1); Stankiewicz-Isidor syndrome (1).